NFATC2 (nuclear factor of activated T cells 2)
Diseases named in the same sentence as NFATC2 in open-access papers (continued):
Sharing a sentence is not in itself a finding about the gene and the disease.
tumor (continued). "To determine whether tumor NFATc2 expression affects the immune microenvironment through galectin‐9, we investigated the effects of NFATc2 and galectin‐9 manipulation on T‐cell proliferation." (PMID 38528665, 2024). "Activation of nuclear factor of activated T cells 2 (NFATC2) could alleviate the functional exhaustion of tumor-infiltrating CD8+ T cells." (PMID 37033959, 2023). "NFATC2 promotes tumor-initiating phenotypes in lung cancer and represses differentiation." (PMID 35406721, 2022). "In such mice, Usp15 deficiency enhanced MDM2/NFATC2 pathway-dependent T-cell activation in vitro and a strong T-cell tumor infiltration in vivo with a major contribution of T-cell-mediated IFN-γ within the anti-tumor immune response." (PMID 35884430, 2022). "It is conceivable that the EWSR1/FUS::NFATC2 fusion might be a very early event in tumor initiation, and additional events are required for progression." (PMID 36555836, 2022). "In summary, NFATC2 acts as a tumor suppressor, whereas NFATC1 exhibits oncogenic activity." (PMID 34309232, 2021). "Our study not only demonstrated the importance of OPN neutralization for anti-tumor effects, but also implied that modulation in calcium/NFATc2/ROS axis could be a novel approach for improving the long-term outcome of NSCLC treatment." (PMID 34187410, 2021). "Namely, NFATC2 is indicated to be a tumor suppressor by the TSGene 2.0 database." (PMID 33273919, 2020). "However, other studies also demonstrated tumor suppressive activity of NFATc2 and NFATc3, suggesting NFAT isoforms play different roles in human cancers in different cellular context." (PMID 31040921, 2019). "In these lesions NFATc2 was expressed in both nuclear and cytoplasmic compartments of tumor cells." (PMID 30710146, 2019). "Tumor nodules of shNFATc2 transfectants removed from SCID mice were negative for EZH2, suggesting that loss of expression of both NFATc2 and EZH2 could contribute to the observed strong anti-tumor effect." (PMID 30710146, 2019). "The NFATc2-inhibited xenografts showed more effective tumor inhibition (5.44 fold, 39.73 fold, respectively) compared to the control group (3.54 fold) (p<0.01) and differences in tumor volumes on the growth curve were statistically significant." (PMID 28737489, 2017). "NFATc1 has oncogenic activity, whereas NFATc2 acts as a tumor suppressor." (PMID 28235034, 2017). "Hence, clinical and experimental evidences support NFATc2 impedes tumor differentiation and negatively affects patient outcome through coupling to SOX2 in lung AD." (PMID 28737489, 2017). "In contrast, NFATc2 overexpression in A549 significantly augmented tumor growth." (PMID 28737489, 2017). "In clinical tumors, high level NFATc2 segregated with impaired tumor differentiation, advanced pathological stage, shorter recurrence-free and overall survivals in NFATc2-positive NSCLC, suggesting NFATc2 mediates the more primitive and aggressive tumor phenotypes." (PMID 28737489, 2017). "However, in other types of malignancies, other isoforms (e.g. NFATc2) were also shown to contribute to the promotion of tumor progression, while inhibitory functions of NFATc2 and NFATc4 were noted." (PMID 25638160, 2015). "This age-associated tumor phenotype was not seen in any of 12 age-matched WT (Nfatc2+/+, N = 6) or hemizygous (Nfatc2+/−N = 6) littermates, and unlike previous reports, no tumors developed in young or old Tob1 KO mice." (PMID 24945807, 2014). "Together, these data indicate that the absence of Nfatc2 creates an environment where the potential loss of intrinsic tumor suppressive function is countered by an unfavorable environment for tumor formation." (PMID 24945807, 2014). "Besides, there have been tumor types with NFATC2 and PATZ1 fusion." (PMID 38427070, 2024). "In particular, NFATC1 may act as an oncogenic factor, whereas NFATC2 acts as a tumor suppressor." (PMID 34309232, 2021). "Similarly, ROS regulation also supported other tumor phenotypes mediated by NFATc2." (PMID 28737489, 2017).
tumor (continued). "The majority of the tumor cells were in the intermediate state, which was governed by the EGR3, NFATC2, and SOX6." (PMID 35903095, 2022). "NFATC2 and HLA-DQB1 played key roles in suppressing tumor growth by increasing T cell machinery through the activation of T cells and antigen presentation, respectively." (PMID 36545214, 2022). "GAL (released from nerves) exerted a nerve–tumor crosstalk by activating GAL2R expressed in tumor cells and by inducing NFATC2-mediated transcription of cyclooxygenase-2 and GAL; then, GAL released from tumor cells promoted neuritogenesis, favoring PNI." (PMID 35954419, 2022). "GALR2 activation subsequently induces tumor cells to secrete pro-inflammatory mediators and neuropeptides that promote invasion and PNI through NFATC2 (nuclear factor of activated T cells 2)-mediated cyclooxygenase-2 expression." (PMID 34885121, 2021). "Inhibition of NFATc2 substantially decreased the expression of proinflammatory cytokines, followed by impaired STAT3 activation and suppressed xenograft tumor growth." (PMID 32041943, 2020). "Here, we revealed that knocking down of NFATc2 using shRNA significantly rescues TNBC cells from OSW‐1‐mediated effects on cell death, tumor growth, invasion and migration, indicating that NFATc2 is involved in OSW‐1 inhibition of TNBC progression." (PMID 32515123, 2020). "In summary, these results demonstrated that NFATc2 participated in OSW‐1‐induced cell death, migration and invasion and tumor suppression." (PMID 32515123, 2020). "EWSR1 is also known to be translocated in 13 other tumour types with at least 17 other fusion partners, common partners being, WT1, ATF1, CREB1, YY1, NFATC2, and others." (PMID 33488267, 2020). "NFATC1, NFATC2, NFATC3, NFATC4, and NFAT5 were all highly expressed in the tumor tissue of the TCGA dataset compared with normal tissue of the GTEx dataset." (PMID 31827081, 2019). "Compared to the MRPS16‐KD U87 cells‐inoculated mice, the mice inoculated with MRPS16‐KD + NFATC2‐OE U87 cells had significantly larger and faster growing tumours, but they did not have statistically affected overall survival." (PMID 41578162, 2026). "Moreover, our analysis of the TCGA datasets also revealed a significant positive correlation between NFATC2 and PDCD1 across six distinct tumor types." (PMID 37833788, 2023). "Activated NFATC2 in fibroblast NIH3T3 cells may block the cell cycle and inhibit cell transformation, showing potential to suppress the tumor, while activated NFATC1 promotes cell proliferation and malignant transformation of carcinogenic properties." (PMID 34309232, 2021). "For example, NFAT1 (NFATc2) can cooperate with the Ras/Ras/MEK/ERK pathway to induce apoptosis in NIH3T3 fibroblasts, and the activation of NFAT1 can shift the oncogenic Ras pathway to act as a tumor suppressor." (PMID 34350189, 2021). "Finally, to elucidate the molecular mechanism of OSW‐1 in TNBC, we performed RNA‐sequencing and cellular functions and identified NFATc2 as a pivotal factor for OSW‐1‐mediated effects on cell death, tumor growth, invasion, and migration." (PMID 32515123, 2020). "By IHC in tumor nodules, NFATc2 shRNA transfectants lacked expression of NFATc2 and of EZH2, compared to control transfectants." (PMID 30710146, 2019). "In three out of four lesions the tumor was positive for NFATc2, ZEB1 and N-cadherin, but lacked MITF." (PMID 30710146, 2019). "In a fourth lesion the tumor expressed NFATc2 and ZEB1, but was negative for N-Cadherin and expressed MITF." (PMID 30710146, 2019). "Kaplan-Meier analysis showed that the patients whose tumor was positive for NFATc2 expression had significantly better survival than the patients whose tumor was negative for NFATc2." (PMID 26795951, 2016). "The median survival of these 72 cases was 64.5 months, significantly better than 49.4 months in the 18 patients whose tumor lacked NFATc2 expression." (PMID 26795951, 2016).
tumor (continued). "Finally, to study the molecular mechanism of how OSW‐1 inhibits TNBC, we performed RNA‐sequencing and cellular functions and considered that NFATc2 may mediate the effect of OSW‐1 on cell death, tumor growth, invasion, and migration." (PMID 32515123, 2020). "Besides, to investigate the molecular mechanism of how OSW‐1 inhibits TNBC, we performed RNA sequencing and cellular functions and considered that NFATc2 may act as a pivotal role in OSW‐1‐induced cell death, tumor growth, invasion, migration." (PMID 32515123, 2020). "Finally, we performed RNA‐sequencing and cellular functions to investigate the molecular mechanism of how OSW‐1 inhibits TNBC, and identified NFATc2 may as a pivotal factor for OSW‐1‐mediated effects on cell death, tumor growth, invasion, and migration." (PMID 32515123, 2020). "Using IHC, high level activated NFATc2 expression with intense and widespread nuclear staining were detected in 41 of 102 (40.2%) excised primary NSCLC, while 61 (59.8%) showed low expression with weak nuclear and/or cytoplasmic staining in isolated or small clusters of tumor cells." (PMID 28737489, 2017). "Moreover, lack of NFATc2 resulted in an elevated tumor formation induced by the tumor promoter methylcholanthrene." (PMID 22764736, 2012). "In summary, our data suggested that Ct-HBx downregulated the expression of TXNIP by transactivation through the transcription repressor NFATC2, then TXNIP exerted its tumor-suppressing function in HBV-induced HCC by negative regulating glycolytic metabolism." (PMID 33323975, 2021). "We first examined messenger RNA (mRNA) expression of NFAT family members (NFATc1, NFATc2, NFATc3, NFATc4, and NFAT5) in 30 pairs of HCC tumor tissues (T) and corresponding adjacent nontumor tissues (NT) by qRT‐PCR." (PMID 30085405, 2018).
cancer (70 papers, 2013 to 2025). A tumor composed of atypical neoplastic, often pleomorphic cells that invade other tissues. "There is a wide range of cancers associated with the dysregulation of NFATc2, such as colon cancer, pancreatic carcinoma, glioblastoma, and colorectal carcinoma." (PMID 39822413, 2024). "It has been reported that NFAT family including NFATc1, NFATc2, NFATc3, and NFATc4 were closely associated with many kinds of cancers." (PMID 31823518, 2020). "In summary, this study demonstrates the calcium signaling molecule NFATc2 enhances functional characteristics associated with cancer stemness phenotype." (PMID 28737489, 2017). "Our analysis identified numerous SIR-associated mutations in oncogenes (e.g., MECOM, NFATC2) and tumor suppressor genes (e.g., LRP1B, PTPRD), as well as in cancer-associated lncRNAs (e.g., MALAT1, NEAT1)." (PMID 41153425, 2025). "The remaining four families shared variants between the affected members in genes potentially involved in cancer development: NFATC2 (c.1101-1G>A, p. ?" (PMID 36765901, 2023). "Among the 49 VUS identified in the index patient 1, two genes were cancer-related: NTRK1c.16C > T and NFATC2 c.1952G > A. Gene fusions involving NTRK1 can confer oncogenic potential in several tumors, including BC and CRC." (PMID 37628631, 2023). "Last, we demonstrated that silencing NFATc2 successfully repressed these two EtOH-induced events in OSCC, suggesting a dual role of NFATc2 in the regulation of glycolysis and cancer stemness." (PMID 36077186, 2022). "Taken together, our results indicate that activation of NFATc2 is required to maintain increased cancer stemness and aerobic glycolysis in the EtOH-exposed OSCC cells." (PMID 36077186, 2022). "Taken together, NFATc2 mRNA expression appears to have a biologic connection with the mTOR pathway across cancer types." (PMID 34021224, 2021). "Pan-cancer analyses utilizing large in vitro and clinical datasets suggest a strong correlation between NFATc2 expression and mTOR pathway activation." (PMID 34021224, 2021). "In total, 24 of the 33 TCGA datasets (72.7%) exhibited statistically significant activation of RICTOR signaling in NFATc2-High cancers." (PMID 34021224, 2021). "By trans-element analysis from the set of altered enhancers, we successfully identified IRF2, RELA, NFATC2, etc., as essential TFs involved in cancer cell growth and migration, possibly via establishing oncogenic enhancer programs." (PMID 34294701, 2021). "We then assessed the expression level of the STAT3/MSK1/NFATc2 axis across 31 cancer cohorts available through the TCGA and the Genotype-Tissue Expression (GTEx) dataset." (PMID 32041943, 2020). "This evidence suggested that NFATc2 is functionally linked to FOXM1 and EZH2, two genes known to regulate mesenchymal programs in cancer cells." (PMID 30710146, 2019). "Impaired mitochondria activate downstream signaling pathways such as HIF-1α and NFATc2, and downregulates the expression of Kv1.5 in cancer cells and proliferating VSMCs." (PMID 31083380, 2019). "Integrating the in vitro and in vivo data of various combinations of multiple cell lines and cancer drug treatments, the enhancing effect of NFATc2 on drug resistance to cytotoxic and targeted therapy was demonstrated." (PMID 28737489, 2017). "In its turn, IGF2 is a trigger molecule of the MAPK signaling cascade, where the signaling converges on the transcription factor NFATC2 that induces transcription of the genes from a genetic network determining the cancer properties of cells." (PMID 28031533, 2017). "So, the effect on tumorigenesis and cancer migration likely depended on the differential activation of NFATc1 and NFATc2 in different cancers." (PMID 28235034, 2017). "Our data also distinguish a different SOX2 enhancer region accessible to NFATc2 which functions not only in the presence of KRAS mutation (A549, PDCL#24) but also in EGFR mutant (HCC827) cancers." (PMID 28737489, 2017).
cancer (continued). "We have shown NFATc2 augments cancer resistance with more prominent effects on tumors treated by cytotoxic chemotherapy." (PMID 28737489, 2017). "When NFATc2 was removed from the cells, they formed smaller tumors and were more sensitive to drug treatment compared to cancer cells with NFATc2." (PMID 28737489, 2017). "Previous research has shown that in many types of cancer, the protein NFATc2 helps cancer cells to grow and spread." (PMID 28737489, 2017). "PPP3CA is reported to interact with NFATs (NFATc1, NFATc2, NFATc3 and NFATc4) transcriptional factors, and have a crucial role in the regulation of immune response, and invasiveness of cancer cells." (PMID 28881575, 2017). "NFATc2 was overexpressed in multiple cancer types, and its depletion suppressed migration/invasion of cancer cells." (PMID 27259269, 2016). "Mechanistically, our findings reveal that manidipine reduces drug efflux activity in resistant cancer cells by modulating intracellular calcium concentrations and targeting nuclear factor of activated T cells 2 (NFAT2), ultimately re-sensitizing these cells to chemotherapy." (PMID 41154347, 2025). "Overall, CYP1B1, NTRK1, and NFATC2 are not related to cancer risk but have potential roles as prognostic markers and actionable drug targets." (PMID 37628631, 2023). "In addition, six tumor suppressor genes previously implicated in cancer (BTK, CHD1, FN1, NFATC2, NOTCH1, and NRP1) were found in at least two samples." (PMID 34489456, 2021). "OPNc might be a potential factor to transmit a stimulation signal to adjacent cancer cells and confer an adaptive response to pharmacological insults via Ca2+/NFATc2/ROS signaling." (PMID 34187410, 2021). "In the long run, the combination of classic cancer treatments and new treatment strategies for Ca2+/NFATc2/ROS axis could make the treatment of NSCLC patients more effective." (PMID 34187410, 2021). "Our findings suggested that OPNc might be a potential factor to transmit environmental signals to cancer cells and confer an adaptive response to pharmacological effects via Ca2+/NFATc2/ROS signaling." (PMID 34187410, 2021). "To understand the molecular mechanism through which NFATc2 mediates cancer cell stemness and drug resistance, we hypothesize NFATc2 might be linked to the pluripotency machinery through its regulatory action." (PMID 28737489, 2017). "Normal B and cancer 1 clusters shared inflammatory markers CCL2, TNFRSF12A, and IL1R1, pathways including TNFα, IL, and Myc signaling, and activity of inflammation, hypoxia, and lipid metabolism–associated transcription factors NFATC2, ARNT, PPARA, and PPARGC1A." (PMID 40215177, 2025). "Furthermore, the expression of these genes was increased by chronic EtOH exposure in OSCC, suggesting that they could be potential candidates to investigate downstream targets of NFATc2-regulated glycolysis and cancer stemness." (PMID 36077186, 2022). "Super-enhancers have been found in genes involved in T-cell activation (IL2RA/CD25, CD30, and FYN) and known cancer genes (TP73, CCR4, TIAM2, NFATC1, NFATC2, and PIK3R1) in ATL cells." (PMID 38791169, 2024). "Recent studies have reported different prognostic values of NFATc2 in cancer, but our own investigations have shown that NFATc2 supports TIC functions in LUAD and that high NFATc2 expression predicts adverse outcomes." (PMID 38528665, 2024). "In our study, we found that silencing NFATc2 in the EtOH-exposed OSCC cells resulted in a decrease in multiple genes involved in glycolysis and cancer stemness, including HIF1α, TP1, ENO1, PKM2, ALDH1A, Bmi1, and Oct4 (data not shown)." (PMID 36077186, 2022). "Mechanistic investigations identified through the NFATc2/SOX2/ALDH1A1 axis, oxidative stress induced by cancer drug treatment is attenuated, leading to increased resistance in a mutation-independent manner." (PMID 34187410, 2021).